TMPRSS2 (transmembrane serine protease 2)
Diseases named in the same sentence as TMPRSS2 in open-access papers (continued):
Sharing a sentence is not in itself a finding about the gene and the disease.
tumor (continued). "In the current work, we performed a comprehensive study of LPCa, considering the risk groups, the degree of differentiation of the tumor cells (ISUP classification), and inclusion in the TMPRSS2-ERG molecular subtype based on RNA-Seq profiling." (PMID 37298233, 2023). "The TMPRSS2: ERG gene fusion is the most frequent genomic alteration in several tumour cases and results in overexpression of the transcription factor ERG." (PMID 37287057, 2023). "In the tumor tissue, TMPRSS2 was negatively correlated with CD8+ T cells in LUAD cohort but positively correlated in LUSC cohort." (PMID 36992839, 2023). "There were also decreases seen in the expression of AR- and AR-V7-regulated genes in RNA extracted from the tumor tissues, though only the decreases in TMPRSS2 and EDN2 were significant." (PMID 37046780, 2023). "We found that in LUAD, compared with normal tissues, AR was significantly positively correlated with TMPRSS2 in tumor tissues, this was also confirmed in the protein expression levels of TMPRSS2 in different sexes." (PMID 36992839, 2023). "A nuclear ERG expression was observed for the C901 primary tumor and PDX, as well as in the adenocarcinoma component of human tumor C1022, consistent with the TMPRSS2-ERG fusion detected in C901 and C1022 PDX." (PMID 37305585, 2023). "RNA was extracted from tumor tissues, and qPCR analyses of AR and AR-V7 regulated genes revealed that there were significant decreases in TMPRSS2 and EDN2 expressions in the bicalutamide and α-mangostin groups." (PMID 37046780, 2023). "We examined TMPRSS2 protein levels in two tissue microarrays containing 63 and 78 paired tumor and normal tissues, respectively, from LUAD and LUSC patient cohorts." (PMID 36992839, 2023). "Because a low level of PSAP immunostaining was strongly linked to TMPRSS2:ERG fusion, as detected by IHC and FISH (p < 0.0001 each), associations with tumor phenotype and prognosis were also separately analyzed in cohorts of ERG-negative and positive tumors." (PMID 37892063, 2023). "To delineate the role of TMPRSS2 in promoting tumor growth, we examined the effects of TMPRSS2 depletion on tumor growth." (PMID 36975376, 2023). "FBXO45 was associated with shortened biochemical-free survival, which was pronounced for the TMPRSS2–ERG-positive tumours." (PMID 36980776, 2023). "TMPRSS2-ERG expression has been detected during tumor initiation/progression in 50–60% of PCa patients." (PMID 37370750, 2023). "TMPRSS2 plays a role in many pathophysiological processes, including digestion, tissue remodeling, inflammation, tumor cell infiltration, apoptosis, and pain." (PMID 36992839, 2023). "The association between TMPRSS2 and Treg, monocyte and DC is consistent in LUAD and LUSC tumor tissues." (PMID 36992839, 2023). "Our results uncovered the key function of TMPRSS2 in tumor prognosis and provided an insight into the prognosis affected by tumor immune cells." (PMID 35558557, 2022). "For example, there is some suggestion from their predominantly clonal presence in tumour samples that gain‐of‐function SVs, including certain recurrent oncogenic fusions such as TMPRSS2‐ESG and BRAF‐KIAA1549, occur early in tumour development." (PMID 35355264, 2022). "Clinical studies have found that there is a significant correlation between the expression of TMPRSS2 and the prognosis of some tumor patients." (PMID 35281819, 2022). "Clinically, the expression of TMPRSS2-ERG (e2e4) was elevated in tumor tissues and indicated poor clinical prognosis, whereas the parental wild type transcripts had no such association." (PMID 36088396, 2022).
tumor (continued). "With further investigation of TMPRSS2-ERG gene fusion-positive tumours, 17/33 of them harbour multiple SV events of different SV types in addition to deletion and translocation events." (PMID 36045381, 2022). "Due to the lower expression of TMPRSS2 in a variety of tumour tissues, we evaluated the gene promoter of TMPRSS2." (PMID 34951103, 2022). "Data evaluation uncovered some CNAs associated with tumor recurrence, in particular, gain of TGFB2 and gain or loss of TMPRSS2." (PMID 35841413, 2022). "PCa tumor cells are driven by a number of oncogenic alterations including highly prevalent gene fusion events such as TMPRSS2-ERG and others involving ETS family transcription factors such as ETV1/4/51,10–12." (PMID 35013146, 2022). "Specifically, we found that the GILncSig was significantly linked to the tumor mutation phenotype and to PTEN, CDK12, SPOP, and TMPRSS2 expression in PCa, all of which are vital signs of genomic instability." (PMID 35860569, 2022). "TMPRSS2 loss was also significantly increased in NMI-CSCs; however, TGCA data showed an association of both CN gain and loss with tumor recurrence." (PMID 35841413, 2022). "GEPIA2 has been explored to dynamically analyze the differential expression of TMPRSS2 in normal and tumor tissues, including RNA sequencing expression data of more than 9,000 tumor samples and more than 8,000 normal samples from TCGA and GTEx." (PMID 35281819, 2022). "High levels of TMPRSS2 also facilitate the tumor growth, progression, invasion and metastasis by modulating the activation of matriptase and the integrity of the ECM network." (PMID 35017320, 2022). "The observed findings revealed that the expression of TMPRSS2 was considerably decreased in many tumour tissues." (PMID 34951103, 2022). "SLC45A3-ERG, identified in 2/115 (1.7%) tumours from African patients, after TMPRSS2-ERG is the second most common fusion event in ERG positive PCa tumours, while SLC45A3-ETV1 fusion has also been reported." (PMID 36045381, 2022). "More importantly, studies have shown that not only does sGC inhibitor treatment suppress tumor growth and proliferation in TMPRSS2-ERG-positive PCa xerographs, but that it can also act strategically with an AR antagonist such as enzalutamide." (PMID 35563163, 2022). "We examined 19 tumor samples from Sardinian patients in which RNA was available (historical FFPET samples) for possible TMPRSS2-ERG fusions." (PMID 33391440, 2021). "Using qPCR, we assessed the expression of TMPRSS2–ERG transcript in 72 tumor samples of PCa and in paired adjacent normal tissues obtained from Russian patients." (PMID 34205581, 2021). "Compared with normal tissues, NRP1 and TMPRSS2 promoters in LUAD and LUSC both show increased methylation, consistent with the decreased NRP1 and TMPRSS2 expression in tumor tissues." (PMID 34168096, 2021). "Comparison with whole-genome sequencing data revealed that most genomic breakpoints are not, or minimally, transcribed while, in contrast, the genomic breakpoints of all 32 TMPRSS2-ERG–positive tumours were present at RNA level." (PMID 34891161, 2021). "Detecting TMPRSS2:ERG fusion in urine was found to be associated with PCa detection, mortality and with tumor volume, and high GS." (PMID 34503059, 2021). "Tumor type-specific deviations from the primary ACE2/TMPRSS2 cluster were observed for prostate (r = − 0.05, m = 0.06) and GI cancers (r = 0.27, m = 0.35), while expression in NSCLC tumors (r = 0.07, m = 0.46) largely overlapped with the primary cluster." (PMID 33707526, 2021). "We systematically investigated the expression of ACE2 and TMPRSS2 in human tumor and normal colorectal tissues by using both bulk and single-cell RNA-sequencing datasets, and found both receptors to be highly expressed in colorectal epithelial cells." (PMID 33479506, 2021). "We found in both bulk and single-cell RNA-seq profiles that ACE2 and TMPRSS2 were expressed at high levels on tumor and normal colorectal epithelial tissues." (PMID 33479506, 2021).
tumor (continued). "Taken together, our results suggest that inflamed tissues such as the cirrhotic liver harbored a higher number of ACE2+/TMPRSS2+ epithelial progenitors when compared with normal and tumor tissues." (PMID 33968947, 2021). "TMPRSS2-ERG-targeted gene silencing therapy using liposomal nanovectors suppressed tumor growth in a VCaP xenograft model and enhanced the efficacy of docetaxel chemotherapy." (PMID 33634124, 2021). "Both NRP1 and TMPRSS2 are decreased in tumor tissues of LUAD and LUSC compared with paired normal tissues." (PMID 34168096, 2021). "What’s more, two same gene mutations of KMT2A and TMPRSS2 were checked out in GFAP separated CTCs and tumor tissue." (PMID 33208163, 2020). "Additional experiments were performed to test the effects of remdesivir and VS-6766 or other MEKi on ACE2, TMPRSS2, and IL-6 in tumor and normal cell lines." (PMID 33245731, 2020). "The protein expression of TMPRSS2 was significantly reduced in normal tissue, and the protein level was significantly elevated in tumor tissue." (PMID 33193689, 2020). "In general, TMPRSS2 primarily affects tumor metastasis by intervening in the signaling pathway, but the mechanism of its influence on the prognosis of PRAD is still unclear." (PMID 33193689, 2020). "We also explored the expression of TMPRSS2 between tumor and normal tissues and conducted IHC in the HPA database." (PMID 33193689, 2020). "To differentiate different types of PC explicitly with respect to tumor grade and TMPRSS2-ERG status, we carried out a comprehensive metabolomics analysis on intact prostate tissue specimens to identify suitable metabolic markers." (PMID 32423389, 2020). "Treatment with flutamide, one of the gold-standard treatments of PCa, and TMPRSS2-ERG siRNA results in similar inhibition of tumor growth in tumor-bearing mice, signifying high efficacy of siRNA treatment in impeding PCa progression." (PMID 33287240, 2020). "We demonstrated that SFRP1 protein increased ERG expression by promoting cellular migration in vitro and increasing tumor growth in vivo in PCa cells with the TMPRSS2-ERG fusion." (PMID 32694934, 2020). "The TIMER database based on the TCGA database was used to reveal that TMPRSS2 was also significantly elevated in PRAD, suggesting that tumor tissues in PRAD were more susceptible to SARS-COV-2 infection." (PMID 33193689, 2020). "Two samples (20%) were found methylated in 2D and 3D cultures and 6 samples were also observed as methylated (60%) in primary tumor tissue for TMPRSS2 (P>0.05)." (PMID 30792990, 2019). "All six HGPIN foci displayed the same tumor-specific TMPRSS2-ERG fusion breakpoint, thus indicating they are clonally related to the adjacent invasive GP3 and GP4 tumor." (PMID 31366128, 2019). "ROCK1 up regulation was associated with androgen receptor (AR) expression, TMPRSS2:ERG fusion, genomic deletions of the PTEN tumor suppressor, as well as recurrent deletions at chromosomes 3p, 5q, 6q." (PMID 31557128, 2019). "By RNA sequencing, we determined the TMPRSS2-ERG fusion status of each tumour sample in the RP cohort." (PMID 31275657, 2019). "In contrast, NCOA2, VEGFA, ACPP, KLF4, and TMPRSS2 had significantly higher tumor vs. normal ratio in BCR cases." (PMID 31741711, 2019). "The role of ETS2 as a tumor suppressor is also supported by studies showing that PCa with TMPRSS2-ERG fusions generated through the deletion of a region containing ETS2 among other genes, represent a more aggressive and hormone-refractory disease." (PMID 31487842, 2019). "Although genomic instability is assumed to increase with tumor progression, we show that Black South African men with significant high‐grade PCa have lower frequencies of TMPRSS2‐ERG fusion than men of European ancestry." (PMID 31090091, 2019). "For each tumor, we dissected 4–5 separate frozen regions and determined the mRNA expression of TMPRSS2, GPI and ENO1 with qRT-PCR." (PMID 30478344, 2018).
tumor (continued). "The classification performance was similar in patient subsets based on tumor TMPRSS2:ERG fusion status." (PMID 29137428, 2017). "Upon depletion of KDMA1 using siRNA, VEGF-A expression was also decreased, which in turn blocked androgen-induced VEGF-A, PSA and Tmprss2 expression, suggesting a role for miR-329-3p as a tumor suppressor." (PMID 28621736, 2017). "TMPRSS2 (transmembrane protease serine 2), an androgen-regulated membrane-anchored serine protease, stimulated a proteolytic cascade that mediated androgen induced PCa cell invasion, tumor growth, and metastasis." (PMID 29152153, 2017). "We developed bioluminescent cell lines expressing the TMPRSS2-ERG fusion in order to assess its role in tumor growth and bone metastasis appearance in a mouse model." (PMID 28055969, 2017). "We have reported that mRNA expression of TMPRSS2-ERG and SLC45A3-ERG rearrangements plus PTEN loss define an aggressive tumor subset." (PMID 29088771, 2017). "Altogether, these observations show that the fusion TMPRSS2-ERG plays an important role tumor cell dissemination into the bone, by increasing the incidence of bone metastases in hind limbs, in the spine and globally." (PMID 28055969, 2017). "Confirmation of the TMPRSS2-ERG status was obtained on the tumor sample by immunohistochemistry with anti-ERG." (PMID 28055969, 2017). "Comparison of adjacent benign and tumor tissue revealed a significant increase in SOX9 mRNA expression in TMPRSS2:ERG fusion-positive tumors (P = 0.0012), while the expression of SOX9 in fusion-negative tumors resembled that of benign tissue (P = 0.60)." (PMID 27798103, 2016). "The data also suggest that presence of a 6q15 deletion including MAP3K7 - either directly or indirectly - prevents tumor cells from developing TMPRSS2:ERG fusions." (PMID 26684029, 2016). "Deletion of Pten in Tmprss2-positive cells of adult mice generated neoplasia only in the prostate, while deletion of Apc in these cells generated neoplasia only in the GI tract." (PMID 27536883, 2016). "Each tumor was found to exhibit high levels of transcripts encoding the AR and AR-regulated genes such as KLK3/PSA and TMPRSS2, indicating an active AR transcriptional program, an important clinical finding for prioritizing therapeutic options." (PMID 27167109, 2016). "In their study, a total of 24 out of 37 (65 %) patients with positive TMPRSS2 rearrangements had pathologic tumour stage ≤ pT2b." (PMID 27377958, 2016). "Amazingly, a significant downregulation of PDE4D7 between low grade (pGleason ⩽3+4) vs high grade (pGleason ⩾4+3) tumours was only observed in patients possessing the TMPRSS2-ERG gene fusion." (PMID 26575822, 2015). "The nanoparticles of siRNA TMPRSS2-ERG-squalene injected intravenously in SCID mice reduced growth of VCaP xenografted tumours, inhibited oncoprotein expression and partially restored differentiation (decrease in Ki67)." (PMID 25933120, 2015). "It is significant that in TMPRSS2-ERG-positive tumour samples the expression of PDE4D7 is negatively correlated with increasing pGleason, highlighting the transient nature of PDE4D7 upregulation." (PMID 26575822, 2015). "VEGFA, PKIB and TMPRSS2 were increased by FGF23 stimulation in LNCaP cells while the tumor suppressor TXNIP was decreased." (PMID 26019137, 2015). "For the cell lines, xenografts, primary tumours without progression and primary tumours with progression to BCR or CR, as well as CRPC tumours, the status of the TMPRSS2-ERG rearrangement is indicated." (PMID 26575822, 2015). "Comparative analysis of the TMPRSS2 promoter upstream sequences among different species revealed the conservation of binding sites for the androgen inducible NKX3.1 tumor suppressor." (PMID 24418414, 2014). "In the current study evaluation of conserved regulatory elements of TMPRSS2 promoter upstream sequences revealed conservation of binding sites for the NKX3.1 tumor suppressor." (PMID 24418414, 2014).
tumor (continued). "Novel associations between TMPRSS2-ERG and alterations in the tumor stroma, for example, increased vascular density, hyaluronan and PDGFRβ and decreased Caveolin-1, all known to be associated with an aggressive disease, were found." (PMID 24505269, 2014). "In the study, we observed that tumour ROIs in radical prostatectomy specimens bore chromosomal abnormalities, including MYC amplification/gain, LPL and PTEN loss, TMPRSS2 rearrangement, as well as general aneuploidy." (PMID 24568597, 2014). "The recurrent TMPRSS2-ETS fusion is by far the most common rearrangement described in any neoplasm, since it has been found in approximately 50% of all PCa cases examined." (PMID 23708091, 2013). "Specific genetic rearrangements that drive tumor progression are relatively rare in solid cancers, but the TMPRSS2-ERG fusion is a notable exception and is observed in about 50% of prostate tumors." (PMID 24199173, 2013). "In conclusion, our data suggest that the TMPRSS2-ERG gene fusion marks a molecularly distinct tumor entity with substantial transcriptional modulation." (PMID 22142399, 2011). "This metastasis originated from the LHSR TMPRSS2/ERG primary tumor, as it stained positive with human-specific anti-AR antibody." (PMID 21747944, 2011). "Even tumor parts with different TMPRSS2-ERG gene fusion status are remarkably identical with regard to small nuclear variations." (PMID 21958464, 2011). "In both the Toronto and Swedish cohorts, ERG was uniquely the most significant differentially regulated transcript in TMPRSS2–ERG fusion-positive tumours." (PMID 20068566, 2010). "TMPRSS2–ERG T1/E4 fusion-positive tumours had differentially regulated mRNAs observed in multiple studies, the most significant one coded for ERG." (PMID 20068566, 2010). "RNA from radical prostatectomy tumour specimens was analysed using cDNA-mediated, annealing, selection, extension and ligation (DASL) to determine mRNAs associated with TMPRSS2–ERG T1/E4 fusion and prognostic of biochemical recurrence." (PMID 20068566, 2010). "Using an FDR ⩽5% yielded 51 genes differentially regulated in TMPRSS2–ERG fusion-positive tumours in the Toronto cohort." (PMID 20068566, 2010). "In our tumor series, 11 of the 14 ERGhigh tumors (79%) were positive for the TMPRSS2: ERGa fusion transcript assessed by end-point RT-PCR." (PMID 20479932, 2010). "On the basis of the Kaplan–Meier survival estimates, the group of patients who had tumours with TMPRSS2:ERG gene fusion had a much greater rate of recurrence at 5 years (58.4%) than patients who lacked the fusion gene (8.1%; P<0.0001)." (PMID 17971772, 2007). "Therefore, understanding the expression of TMPRSS2 in tumor patients and its relationship with prognosis is helpful to elucidate the reasons why tumor patients are more prone to COVID‐19 infection, and to determine whether tumor immunotherapy affects their susceptibility." (PMID 40145441, 2025). "Patients with higher TMPRSS2 expression demonstrated better overall survival rates, implying that TMPRSS2 may enhance immune‐mediated tumor suppression." (PMID 40145441, 2025). "The expression level of TMPRSS2 is closely related to tumor immunity and prognosis." (PMID 40145441, 2025). "Expression of ACE2 and TMPRSS2 in tumor tissues in relation to immune cells and prognosis." (PMID 40145441, 2025). "Notably, TMPRSS2 expression is correlated with immune cell infiltration, suggesting its role in modulating the tumor microenvironment." (PMID 40145441, 2025). "Therefore, the targeting of TMPRSS2‐mediated tumor downstream signaling pathways has therapeutic potential, but the underlying mechanisms remain to be determined." (PMID 40145441, 2025). "In addition, chronic inflammation can promote tumor heterogeneity through enhancing genetic divergence of tumor cells, such as TMPRSS2: ERG fusion." (PMID 39891849, 2025). "Contributing factors may include genetic predisposition and molecular features such as elevated TMPRSS2:ERG fusions and aggressive tumor biology." (PMID 40792342, 2025).